DCLK1 (doublecortin like kinase 1)
Diseases named in the same sentence as DCLK1 in open-access papers (continued):
Sharing a sentence is not in itself a finding about the gene and the disease.
intestinal tumors (11 papers, 2014 to 2024). "We utilized the adenomatous polyposis coli mutation-induced (ApcMin/+) mouse model, in which DCLK1 is markedly overexpressed in intestinal tumors." (PMID 35910805, 2022). "To test the therapeutic effect of DCLK1-IN-1, we inoculated murine intestinal tumor cells (MC-38) into a syngeneic mouse model that is applicable for monitoring PGE2-induced microenvironmental changes, including changes in inflammation and immune responses." (PMID 35910805, 2022). "DCLK1+Lgr5+ cells can be identified in intestinal tumours that arose following activation of Wnt signaling in Lgr5+ stem cells, and a recent study confirmed DCLK1 as a downstream target of Wnt signaling." (PMID 36263033, 2022). "In intestinal tumours, DCLK1 often co-expresses with LGR5 at crypt base and DCLK1+LGR5+ stem cells are able to continuously produce tumour progeny under the APC+/− mice." (PMID 28195176, 2017). "DCLK1 was recently identified as the only marker that accurately distinguishes CSCs from intestinal tumours from normal stem cells." (PMID 26437858, 2015). "Multiple intestinal tumor onset and progression in the elderly ApcMin/+ mice allowed us to investigate how Dclk1 supports intestinal tumorigenesis and to identify novel strategies for cancer prevention and potential treatment." (PMID 25211188, 2014). "Interestingly, AOM treatment alone induced significant Dclk1 staining in the intestinal tumors and more so in the colon." (PMID 31040926, 2019). "It was shown in a recent study that administration of AOM alone or combined with Citrobacter rodentium infection increased proliferation and Dclk1-positive cancer stem cell frequency in intestinal tumors of Apc1638N/+ mice indicating enhanced tumorigenesis in line with our results." (PMID 31681563, 2019). "Doublecortin-like kinase 1 (DCLK1) is considered as one of the most specific CSC markers; it does not mark normal stem cells in the intestine but instead marks CSCs that continuously produce tumor cell progeny in intestinal tumors 4-6." (PMID 35910805, 2022).
pancreatic ductal adenocarcinoma (11 papers, 2015 to 2024). An infiltrating adenocarcinoma that arises from the epithelial cells of the pancreas. "DCLK1 has been identified as an understudied druggable kinase whose overexpression is linked to multiple human cancers such as colorectal and gastric cancer as well as pancreatic ductal carcinoma." (PMID 35830914, 2022). "Especially, Ferguson and Nabet48 discovered DCLK1‐IN‐1, a selective inhibitor of DCLK1, and demonstrated the activity of DCLK1‐IN‐1 against clinically relevant patient‐derived pancreatic ductal carcinoma organoid models." (PMID 35522902, 2022). "Pancreatic ductal adenocarcinoma (PDAC)-based study showed overexpression of KDM3A that increased expression of DCLK1." (PMID 36250024, 2022). "The selective compound DCLK1-IN-1 helped to establish cell motility as a role of DCLK1 in patient-derived pancreatic ductal carcinoma organoids and differentiate results obtained with earlier and less selective probes." (PMID 35830914, 2022). "Intriguingly, DCLK1 kinase inhibitor can inhibit DCLK1+ organoids derived from pancreatic ductal adenocarcinoma patient tumors, indicating that DCLK1 activity and perhaps DCLK1+ TCs or acinar cells are a potential target for pancreatic ductal adenocarcinoma." (PMID 33348546, 2020). "Why do cells that express high levels of DCLK1 show enhanced migration, invasion, and metastasis in human pancreatic ductal adenocarcinoma?" (PMID 26764906, 2016). "Genome-wide next generation sequencing of pancreatic ductal adenocarcinoma (PDAC) from GEM mice revealed significantly increased DclK1 along with inflammatory genes." (PMID 25906749, 2015). "Moreover, pharmacological inhibition of DCLK1 prevented the development of DCLK1+ pancreatic ductal adenocarcinoma (PDAC) in clinically relevant patient-derived PDAC organoid models." (PMID 38062554, 2024). "DCLK1 serves as a molecular marker for pancreatic ductal adenocarcinoma (PDAC)." (PMID 36250024, 2022). "Dclk1+ pancreatic ductal adenocarcinoma (PDAC) cells supply descendant PDAC cells in vivo." (PMID 33393460, 2021). "Importantly, this inhibitor showed significant activity against clinically relevant DCLK1+ patient-derived pancreatic ductal adenocarcinoma organoids." (PMID 33348546, 2020).
pancreatitis (11 papers, 2015 to 2022). Inflammation of the pancreas. "Surprisingly, we found that, although C57Bl/6J mice develop pancreatitis and suffer significant loss of pancreas tissue in response to caerulein, similar to CD-1, we were unable to detect Dclk1+ cells with tall columnar, tuft cell morphology." (PMID 32116793, 2020). "Dclk1+ cells in the normal pancreas harbor the potential function to initiate premalignant lesions when the oncogenic Kras mutation is introduced together with inflammatory stimuli such as caerulein-induced pancreatitis in vivo." (PMID 33393460, 2021). "For instance, acinar cells expressing Dclk1, a microtubule regulator, are quiescent in combination with Kras activation but initiate cancer upon cerulein-induced pancreatitis." (PMID 34209288, 2021). "A previous study showed that Dclk1+ cells can be PDAC initiating cells in the context of pancreatitis and that Dclk1+ cells have stem cell properties to sustain spheroid growth in vitro." (PMID 33393460, 2021). "Doublecortin-like kinase-1 (Dclk1) has been shown to be an essential gene for proper regeneration upon acute and chronic cerulein-induced pancreatitis, as Dclk1+ cells started to proliferate rapidly after injury to repopulate the acinar cell compartment." (PMID 34209288, 2021). "Induction of inflammation/pancreatitis with cerulein in GEM mice increased DclK1, and the novel dual COX/5-lipoxygenase (5-LOX) inhibitor licofelone reduced it." (PMID 25906749, 2015). "Licofelone dramatically inhibited inflammation, proliferation, thereby pancreatitis as well as PanIN lesions and DclK1 expression." (PMID 25906749, 2015). "We observed significantly enhanced pancreatitis along with increased PanIN lesions and increased DclK1 in cerulean-treated GEM." (PMID 25906749, 2015). "Pancreatic tissue from day 1 following caerulein-induced injury was consistent with modest pancreatitis, and strong Dclk1 staining was observed in several small ducts." (PMID 25723399, 2015). "At day 5 following injury severe pancreatitis persisted, and all ductules and ducts stained strongly with Dclk1 antibody." (PMID 25723399, 2015). "At day 3 following injury, characteristics consistent with severe pancreatitis were observed, and all ductules and ducts stained modestly with Dclk1 antibody." (PMID 25723399, 2015). "Our findings of increased Dclk1 expression in the ADM and pancreatitis in C57Bl/6 mice are consistent with recent reports in early stage KCiMist1 and KCPdx1 mice, and Ptf1aCre/+;SOX17OE mice." (PMID 25723399, 2015). "However, differing from the previously noted Dclk1+ quiescent cells, we found that SETD4+ cells not only largely contribute to regeneration in cerulein-induced pancreatitis, but also contribute to pancreas development both in the embryonic and postnatal pancreas." (PMID 34131249, 2021).
renal cell carcinoma (11 papers, 2017 to 2025). "DCLK1 has been reported to be associated with tumorigenic immune infiltrates in gastrointestinal tumor and renal cell carcinoma." (PMID 37069669, 2023). "In order to evaluate the effect of targeting DCLK1 in vivo, we utilized a novel mAb (CBT-15G) as well as a production-ready version of the mAb that we recently reported against DCLK1 in renal cell cancer." (PMID 31467540, 2019). "DCLK1 has been identified to be involved in tumorigenesis of various types of cancer, such as renal cell carcinoma (RCC), pancreatic ductal adenocarcinoma (PDAC), colorectal cancer (CRC) and breast carcinoma (BCA)." (PMID 29246000, 2017). "In addition, high expression of DCLK1 is associated with low CD8+ T cell infiltration, and one study has found that the use of DCLK1-IN-1 in renal cell carcinoma can promote the efficacy of ICIs, which provides new ideas for the treatment of CRC." (PMID 38254219, 2024). "Besides, the expression levels of DCLK1 were upregulated in multiple cancers including renal cell carcinoma (RCC), colorectal cancer (CRC) and PC." (PMID 37069669, 2023). "Furthermore, DCLK1 marks a population of tumour stem-like cells in renal cell carcinoma (RCC)." (PMID 38062554, 2024). "Several studies supported the critical oncogenic role of DCLK1 CSC surface marker in the gastrointestinal (GI), colon, pancreases, and renal cell carcinomas (RCC)." (PMID 35717205, 2022).
cholangiocarcinoma (9 papers, 2015 to 2025). A carcinoma that arises from the intrahepatic biliary tree (intrahepatic cholangiocarcinoma) or from the junction, or adjacent to the junction, of the right and left hepatic ducts (hilar cholangiocarcinoma). "Initially, we assessed the baseline expression of DCLK1 in two cholangiocarcinoma cell lines, RBE and HCCC9810." (PMID 38980538, 2024). "In individuals with cholangiocarcinoma who express DCLK1 at high levels, inhibitors of the PI3K/AKT/mTOR signaling pathway may be an effective therapeutic approach." (PMID 38980538, 2024). "Therefore, based on the results of RNA-Seq analysis, we further explored whether DCLK1 promotes the development of cholangiocarcinoma by activating the PI3K/AKT/mTOR signaling pathway." (PMID 38980538, 2024). "DCLK1 has been described as a CSC associated antigen in colon, pancreatic and even in Cholangiocarcinoma (CCA) tumors." (PMID 33806296, 2021). "For example, distinct peptide mass fingerprints (PMFs) were identified for early versus late recurrence in cholangiocarcinoma (CCA), where peptides such as KNTC1, DCLK1, ALG10, ATR, and BLM were associated with early recurrence, while SERPINA1, TGFB2, and SERPING1 were implicated in late recurrence." (PMID 41008874, 2025). "However, it is still unexplained how DCLK1 impacts the progression of cholangiocarcinoma and the particular procedures by which it encourages tumor advancement in CCA." (PMID 38980538, 2024). "To assess whether DCLK1-mediated alteration in β-catenin correlated with clinical activity, we first analyzed the TCGA database for β-catenin mRNA expression levels in HCC, cholangiocarcinoma, and colorectal adenocarcinoma." (PMID 32601309, 2020).
colon adenocarcinoma (9 papers, 2015 to 2023). "It was, for example, demonstrated that Dclk1 short is the most abundant isoform in colon adenocarcinomas, while normal colon tissues mainly contained Dclk1 long, and Dclk1 was established as marker for intestinal, renal, and liver cancer." (PMID 37594553, 2023). "Further IHC and Western blot analysis showed that Vimentin and DCLK1 were highly expressed in colonic adenocarcinoma of Villin-CXCR7 mice, which was abrogated by Verteporfin." (PMID 36210463, 2022). "However, unlike these two rare examples, extensive methylation of the CGI/promoter of other HOX genes was often associated with the use of an alternative promoter, as previously reported for various genes in prostate cancer cell lines and the DCLK1 gene in human colon adenocarcinoma." (PMID 33720519, 2021). "DCLK1 is most frequently mutated in stomach adenocarcinomas (STAD, 10.6%), uterine corpus endometrial carcinoma (UCEC, 9.2%) and colon adenocarcinomas (COAD, 8.7%), while copy number variation gains are most frequently observed in rectal adenocarcinomas (READ, 69.5%), COAD (56.3%), and STAD (37%)." (PMID 36979969, 2023). "In addition, high DCLK1 expression in the tumor tissues also predicted poor overall survival (OS; p = 0.021 for colon adenocarcinoma (COAD) and p = 0.0002 for stomach adenocarcinoma (STAD)), and progression-free survival (PFI) (p = 0.0086 for COAD and p < 0.0001 for STAD)." (PMID 31979136, 2020).
neuroblastoma (9 papers, 2012 to 2024). Neuroblastoma (NB) is the most common solid, extracranial childhood tumor. "In neuroblastoma tissues, down-regulation of miR-424 has been found to be accompanied by up-regulation of its target gene DCLK1." (PMID 37178445, 2024). "An experiment in neuroblastoma cell lines has revealed down-regulation of miR-424 and up-regulation of its target gene DCLK1 in these cells compared with normal spongiocyte cells." (PMID 37178445, 2024). "DCLK1 has recently been reported to be a significant contributor to proliferation and mitochondrial activity in neuroblastoma cells." (PMID 24885928, 2014). "Our data suggests some bias for TSSIII usage in schizophrenia, producing both D02 (full length DCLK1) and D04 (N-terminal DCL-like region) variants, which have been shown to prevent apoptosis in neuroblastoma cells." (PMID 22558445, 2012). "Moreover, a recent study demonstrated that doxycycline-inducible knockdown of DCLK1 inhibits proliferation, mitochondrial activity, and ATP synthesis in N1E-115 neuroblastoma cells and delays progression of N1E-115 tumor xenografts." (PMID 24885928, 2014). "siRNA-mediated silencing of DCLK1 triggers apoptosis in SHSY5Y neuroblastoma cells." (PMID 24885928, 2014). "In fact, DCLK1 could partially reverse function of miR-424 in neuroblastoma cells." (PMID 37178445, 2024). "For mouse cortex, B104 neuroblastoma cells, and HEK293 cells, we predominantly observed Dclk1 long, while C6 glioblastoma, B35 neuroblastoma, and NIH/3T3 cells expressed both isoforms." (PMID 37594553, 2023).
hepatoma (8 papers, 2013 to 2021). "Here, we demonstrate that DCLK1-overexpressing hepatoma cells develop into spheroids composed of SOX9 + and α-fetoprotein + cells." (PMID 32601309, 2020). "In DCLK1-overexpressing hepatoma cells and livers derived from patients with cirrhosis and HCC, we detected a distinct low molecular weight (48-kDa) β-catenin with an intact N-terminus that was not phosphorylated at Ser33 and Ser37." (PMID 32601309, 2020). "We previously demonstrated that sustained HCV replicon expression in hepatoma cell lines is directly linked to the gain of cancer stem cell (CSC)-like properties and overexpression of CSC markers (DCLK1, Lgr5, CD133, c-Myc)." (PMID 25948779, 2015). "These and other results provide proof-of-concept data that the DCLK1 knockdown is possible in the DCLK1-overexpressing hepatoma cells and such treatment will eventually halt migratory abilities of the tumor cells." (PMID 25948779, 2015). "We also found that treating Huh7.5 human hepatoma cell-derived tumor xenografts with DCLK1-specific siRNA resulted in tumor growth arrest, downregulation of DCLK1, and increased expression of tumor suppressor miRNAs let-7a, miR-200, and miR-143/145." (PMID 26468984, 2015). "Treatment of Huh7.5 human hepatoma cell-derived tumor xenografts with DCLK1-specific siRNA produced tumor growth arrest, DCLK1 downregulation, and increased expression of tumor suppressor miRNAs let-7a, miR-200, and miR-143/145." (PMID 26468984, 2015). "FLV treatment resulted in induction of microtubule bundling, cell-cycle arrest and alterations in cellular DCLK1 distribution in HCV-expressing hepatoma cells." (PMID 24260365, 2013). "The DCLK1-expressing hepatoma cells produce a short form of active β-catenin containing an unphosphorylated N-terminus and a preserved TCF-4 binding capacity, but do not have the C-terminus regulatory region of the full-length β-catenin (92 kDa) that is required to bind E-cadherin." (PMID 32601309, 2020). "DCLK1 overexpression in hepatoma cells also increased phosphorylation of GSK-3β at Ser9." (PMID 32601309, 2020). "We also confirmed clonogenic properties of DCLK1 + hepatoma cells and its lineages." (PMID 32601309, 2020). "Finally, limited evidence suggests that DCLK1-expressing intestinal TCs in the gut can promote tumor progression in hepatocellular carcinoma (HCC) through activating alternative macrophages in tumor microenvironment via secreting IL-25." (PMID 33348546, 2020). "In addition, GSK-3β activities that are required for N-terminus hyperphosphorylation-mediated degradation of β-catenin are downregulated due to increased GSK-3β-Ser9 phosphorylation in DCLK1-overexpressing hepatoma cells." (PMID 32601309, 2020). "We determined soluble E-cadherin levels in the cell culture supernatant of DCLK1-overexpressing hepatoma cells to determine whether DCLK1 overexpression in the liver diseases is related to change in epithelial phenotypes of the cells." (PMID 32601309, 2020). "We previously documented that liver-derived hepatoma cells express high levels of tumor/cancer stem cell (CSC) markers such as Myc, CD133, α-fetoprotein and doublecortin-like kinase (DCLK1, also called DCAMKL-1) in response to HCV replication." (PMID 24260365, 2013). "Doublecortin-like kinase 1 (DCLK1), formerly known as DCAMKL1 and KIAA0369, is one such MAP that is also upregulated in a range of cancers, such as pancreatic, breast, bladder, colorectal, gastric, and hepatocellular carcinoma." (PMID 34310279, 2021). "Spheroids derived from DCLK1-overexpressing hepatoma cells showed high level expression of active β-catenin, α-fetoprotein, and SOX9, suggesting that DCLK1 overexpression induces clonogenicity and dedifferentiated phenotypes in hepatoma cells." (PMID 32601309, 2020). "DCLK1 silencing inhibits S100A9 expression and hepatoma cell migration." (PMID 25948779, 2015). "Hepatoma cells (GS5 and Huh7.5) were infected with lentiviruses expressing untagged human DCLK1." (PMID 24260365, 2013).
hepatoma (continued). "Downregulation of DCLK1 inhibits HCV replication, hepatoma cell migration, tumor growth in an HCC xenograft model, EMT, and expression of myeloid-derived S100A9 protein, which suppresses anti-tumor immunity." (PMID 32601309, 2020).